AHR (aryl hydrocarbon receptor)
Diseases named in the same sentence as AHR in open-access papers (continued):
Sharing a sentence is not in itself a finding about the gene and the disease.
tumor (continued). "By modulating the tumor microenvironment, AhR-targeted therapies could enhance anti-tumor immune responses and improve the efficacy of existing treatments." (PMID 39184676, 2024). "AhR activation impacts both tumor-intrinsic pathways and immune cells in a context-specific manner." (PMID 38339226, 2024). "In addition to influencing the overall polarization state of TAMs, T cell–macrophage crosstalk is critical to anti-tumor immunity and regulated by AhR activation." (PMID 38339226, 2024). "Inhibiting AhR activation polarized TAMs towards a pro-inflammatory state that was parallelled by increased infiltration of effector memory (CD62LnegCD44hi) CD8+ T cells into tumors resulting in suppression of tumor growth." (PMID 39713022, 2024). "Elevated AHR activity, combined with genetic variations and environmental exposures, may amplify AR signaling, leading to more aggressive tumor behavior and resistance to conventional treatments such as ADT." (PMID 39600743, 2024). "Therefore, AhR has great potential in regulating tumor lipid metabolism and worth more further investigation." (PMID 38434684, 2024). "Although AhR activation has been shown to promote carcinogenesis in some studies, others suggest that it may act as a tumor suppressor." (PMID 38518996, 2024). "Moreover, deletion of AhR reduced tumor growth, increased the number of IFNg + CD8 + T-cells, and improved the efficacy of ICI treatment." (PMID 38745196, 2024). "Enhanced expression of IDO1 and TDO2 leads to greater catabolism of tryptophan leading to raised levels of the tryptophan metabolite kynurenine in the tumour, and thereby enhancing activation of the aryl hydrocarbon receptor (AhR) for which kynurenine is an endogenous ligand." (PMID 39048947, 2024). "Further, AhR participates in important cellular and pathological processes, including proliferation, migration, angiogenesis, the control of the immune system, and tumor initiation and progression." (PMID 39200369, 2024). "Furthermore, not only the malignant cells, but also the cells within the tumor microenvironment express high levels of AhR." (PMID 38518996, 2024). "Importantly, knockdown of AhR in mice eliminated the effect of ampicillin on tumor growth, suggesting an AhR-mediated pathway." (PMID 38448800, 2024). "In esophageal cancer, various reports suggest AhR acts as a tumor promoter." (PMID 38807762, 2024). "This leads to the hypothesis that the AhR is chronically activated in tumors, thus facilitating tumor progression." (PMID 39339278, 2024). "Mounting evidence suggests that Kyn-triggered AhR helps tumor cells avoid the immune system." (PMID 38434684, 2024). "The research demonstrated that epigenetic drugs, including DNA methyltransferase inhibitors and histone deacetylase inhibitors, could restore AhR expression and activity, leading to reduced tumor cell viability and enhanced apoptosis." (PMID 39184676, 2024). "AhR activation promotes T cell exhaustion and reduces effector T cell function, but at the same time promotes formation of tissue-resident memory (TRM)-like cells associated with anti-tumor responses and disease control." (PMID 38339226, 2024). "Consequently, Kyn, acting through AHR, suppresses anti-tumor immune responses and promotes tumor cell survival and motility." (PMID 38244584, 2024). "Importantly, the immunoregulatory role of tryptophan metabolite‐mediated AhR signalling in anti‐tumour effects has recently been revealed." (PMID 39568157, 2024). "The kynurenine (Kyn), as an endogenous ligand of AhR, could induce AhR activation when generated in the tumor microenvironment, which promote tolerant phenotype in DCs to mediate the generation and expansion of Tregs." (PMID 40124706, 2024). "Similarly, it has been shown in CD8+ T cells that AhR translocation in the tumor microenvironment, induces 5-HT release leading to CD8+ T cells exhaustion." (PMID 38509264, 2024).
tumor (continued). "The dual role of AhR in modulating AR signaling complicates therapeutic strategies, necessitating personalized approaches based on the unique characteristics of each patient's tumor." (PMID 39184676, 2024). "By integrating our analysis with expression data from exposures to TCDD and expression data from pVHL-defective clear cell renal cell carcinoma (ccRCC), we provide insights into the potential repercussions of an impaired AHR pathway in ccRCC and its subsequent impact on tumour progression." (PMID 39336758, 2024). "Similarly, various tumor cells within the human body have demonstrated that KYN can activate AhR in an autocrine or paracrine manner, further driving cancer progression." (PMID 38883986, 2024). "Interestingly, AhR is known to promote immunosuppression in several tumor types through various mechanisms, including the inhibition of STING activity." (PMID 38459088, 2024). "The metabolites KYNA and I3A, derived from I3P, can activate AHR, promote the differentiation of Tregs, and recruit MDSCs169 Additionally, 13P can suppress ferroptosis in tumor cells by neutralizing free radicals and activating antioxidant stress pathways, thus modulating immunosuppression." (PMID 39492834, 2024). "The role of microbial tryptophan metabolism is also controversial, with some studies suggesting indoles can act as aryl hydrocarbon receptor (AhR) agonists, promoting immune evasion in the tumor microenvironment (TME), and others showing these metabolites can promote anti-tumor immunity." (PMID 38873602, 2024). "We also focus on recent findings to discuss the idea that AhR acts as a receptor for metabolic changes in tumors, which may provide new perspectives on the direction of AhR research in tumor metabolic reprogramming and future therapeutic interventions." (PMID 38434684, 2024). "While more work needs to be done to address the discrepancies, the consensus seems to be that AhR antagonism would be beneficial to promote a tumor-suppressive microenvironment and relieve the immune-suppression often seen associated with the more aggressive tumors." (PMID 38807762, 2024). "Thus, immunosuppressive tumor cytokines and AhR stimulation promote CD83 downregulation and generation of CD83- IDO1+LCs (immature tolerogenic LCs) and/or CD83- IDO1-LCs (real immature LCs)." (PMID 38791968, 2024). "Through AhR signaling, TAMs work against anticancer immunity and tumor growth suppression." (PMID 39371092, 2024). "AhR plays an important role in carcinogenesis and tumor immunity." (PMID 38680496, 2024). "The AhR expression levels in each immune cell type (macrophages, T cells, and Tregs) within the tumor nest were positively correlated with the stromal AhR expression in the corresponding cell type, a pattern consistent with those found for the other cancer types." (PMID 38680496, 2024). "The tumor-suppressive function of AhR has been reviewed recently." (PMID 38518996, 2024). "The interaction between AHR and AR signaling pathways might promote tumor growth and lead to resistance to standard treatments." (PMID 39600743, 2024). "However, the importance of TDO2-mediated tryptophan metabolism in cancer biology has been known for some time, with TDO2-mediated production of kynurenine reported to promote tumour cell survival through activation of the AhR." (PMID 39048947, 2024). "This heightened AHR expression in macrophages led to the generation of Treg cells via PD-L1 upregulation, thereby creating an immune-suppressive environment that promoted tumor cell metastasis." (PMID 39690159, 2024). "Bacteria from the Eggerthellaceae family have been found to produce urolithin, have anti-inflammatory and antioxidant properties, and can also stimulate the AhR (Aryl hydrocarbon receptor) to activate tight junction proteins, thereby having anti-tumor activity." (PMID 39065109, 2024). "Furthermore, the interaction between AHR and AR signaling creates a synergistic effect in AA patients, enhancing tumor aggressiveness." (PMID 39600743, 2024).
tumor (continued). "Furthermore, inhibition of AhR signaling reduces immunosuppression, as demonstrated by lower frequencies of tumor-infiltrating Tregs and macrophages in tumor-bearing mice, leading to reduced tumor growth." (PMID 39474416, 2024). "Furthermore, AhR influences tumor progression independently of AR by regulating genes involved in cell cycle control and apoptosis." (PMID 39184676, 2024). "In preclinical studies, the selective orally active AHR antagonist called IK-175 could impede tumor growth and reverse immunosuppression in mouse tumor models." (PMID 38966172, 2024). "Moreover, once the tumour is established various endogenous and exogenous ligands of AhR continue to support tumour growth and modulation of the tumour microenvironment." (PMID 38974991, 2024). "Therefore, this work can contribute to a better understanding of how flavonoids modulate molecular targets such as AHR, potentially leading to significant advancements in drug development and their application in adjuvant tumor therapy." (PMID 39204085, 2024). "Evidence of the role of AhR in MDSC tumor immunity is limited." (PMID 38339226, 2024). "Because of this AHR antagonists are being actively investigated as new anti-tumor therapy." (PMID 39450255, 2024). "In addition, the activation of the AhR by different molecular compounds can lead to contrasting consequences, including both tumor-suppressing and tumor-promoting." (PMID 38547865, 2024). "The expression of the AhR increases in invasive tumors and has higher nuclear localization than in noncancerous tissue, which indicates that the AhR signaling pathway is active and related to the malignant phenotype of tumor cells." (PMID 39770078, 2024). "Additionally, AhR activation can drive macrophages to acquire an immunosuppressive phenotype, which can mediate chemotherapy resistance in tumor." (PMID 39835132, 2024). "Therefore, AhR activation appears to have a dual role in promoting antitumor immunity and facilitating tumor immune escape, depending on which type of immune cells are involved." (PMID 38518996, 2024). "Our combination strategy of TPME remodeling synergized with immune‐metabolic blockade can establish an inflammatory tumor immune niche via disrupting the IDO1/Kyn/AhR axis‐mediated immune escape, which exerts effective tumoricidal immune activity to inhibit postsurgical ccRCC recurrence." (PMID 38884220, 2024). "Ethnic differences in immune response, potentially driven by variations in AHR activity, may contribute to the differential tumor microenvironments observed between AA and Caucasian men." (PMID 39600743, 2024). "For an example, I3C, an AHR agonist, can reduce inflammatory responses in the gut, but it simultaneously accelerates formation of colonic lesions, which may become a tumor over the long-term." (PMID 39125717, 2024). "Thus, the inhibiting of pathologic AhR activation is the promising method to reroute immunity toward tumor rejection." (PMID 39850551, 2024). "Its anticancer prowess was observed to disrupt the G1/S phase, inducing apoptotic pathways through caspase-3 activation, and orchestrating the downregulation of pivotal cellular regulators such as STAT3, P21, P27, IL-6, and AhR, thereby impeding tumor progression." (PMID 38653790, 2024). "Our results also suggest that activated AhR may contribute to the tumor–stroma interaction (through CYP1A1 and CYP1B1) in diffuse GC." (PMID 39200369, 2024). "Activating the AhR can hinder the ability of macrophages and T cells to exert anti-tumor effects." (PMID 39408347, 2024).
tumor (continued). "Conversely, dietary tryptophan can be metabolised into indole by Lactobacillus, which activates AhR in tumour‐associated macrophages (TAMs), reducing the ability of CD8+ T cells to suppress anti‐tumour immunity and ultimately promoting pancreatic ductal adenocarcinoma development." (PMID 39568157, 2024). "A similar proportion was observed in the High/Medium AHR group; 11 out of 18 were G1 or G2 tumours." (PMID 37760608, 2023). "In this respect, AhR, as a transcription factor that controls a wide array of genes, is capable of both inhibiting oncogene expression and activating the expression of tumor suppressor genes." (PMID 37106727, 2023). "AhR-mediated rewiring of signaling pathways contextually reduced immunological responses and severely impaired natural killer cell-mediated inhibition of tumor progression." (PMID 37830596, 2023). "Such a shift of AHR enrichment peaks was exampled by the AHR peaks on the BACH2 gene encoding a BTB domain basic leucine zipper transcription factor important for cell apoptosis and tumor immunosuppression." (PMID 37151890, 2023). "Subsequently, gavage of A. muciniphila in ABX-treated AhR -deficient ApcMin/+ mice did not reduce both tumor count and size significantly, further supporting the preventive and protective effects of A. muciniphila." (PMID 37781044, 2023). "However, once a tumor is formed, what is less clear is the role of the AHR within the tumor microenvironment." (PMID 37755265, 2023). "Recently, overexpression of IL4I1 was shown to activate AHR and promote tumour progression." (PMID 38062922, 2023). "Taken together, this indicates that in addition to direct effects on HIF-2 signaling in ccRCC tumours, belzutifan may have indirect effects on AHR activation." (PMID 36725335, 2023). "In summary, activation of the TDO2/kynurenine/AHR pathway selectively in mut-MED12 leiomyomas promoted tumor growth and may inform the future development of targeted treatments and precision medicine." (PMID 37607000, 2023). "As expected, NAC pretreatment did not improve the inhibition of tumor growth in AHR(C300A)-mutated tumor-bearing mice." (PMID 38099490, 2023). "Aryl hydrocarbon receptor antagonists also attenuate immunosuppression and inhibit tumor growth." (PMID 37924140, 2023). "Using multiple in vitro models of tumor–adipocyte crosstalk to mimic the bone microenvironment, we identified a novel, non-toxicological role of the adipocyte-secreted factors in the suppression of AhR activity in MM cells." (PMID 37958428, 2023). "Thus, there are several ongoing studies targeting the AHR signaling pathway to enhance antitumor immunity and re-sensitize tumor to chemotherapy." (PMID 37968758, 2023). "The key to understanding the apparent multifaceted role of AhR in tumor development may lie in the diversity of responses regulated by unliganded constitutively active AhR, and upon distinct modes of AhR activation being elicited by its different ligands." (PMID 37696458, 2023). "The kynurenine-activated AhR leads to immunosuppression and tumor-promoting microenvironment." (PMID 37241719, 2023). "For example, the AHR protein, which could be inhibited by flutamide, was significantly upregulated in tumor samples." (PMID 36774361, 2023). "The tumor promoting effects of AhR may also be involved in SCC, but they might be less prominent here." (PMID 37696458, 2023). "Indeed, 3-IAld was found to activate CD8+T cells for antitumor activity via AhR once produced at the tumor site and to fail to promote tumor growth when administered in tumor-bearing mice." (PMID 36839828, 2023). "In this regard, BP might hijack the AhR pathway to impair DC-elicited tumor immunosurveillance, which contributes to its carcinogenic potential." (PMID 37175508, 2023). "AhR+/+ TRAMP mice demonstrated markedly reduced tumor development." (PMID 37830596, 2023). "Together, these results indicated that AhR might inhibit tumor cell ferroptosis by regulating SLC7A11 expression." (PMID 37056388, 2023).
tumor (continued). "The AHR may contribute to inflammatory signaling within the tumor microenvironment through the combinatorial regulation of several chemokine and cytokine genes." (PMID 37755265, 2023). "The aryl hydrocarbon receptor (AHR) can enhance tumor malignancy and inhibit antitumor immunity." (PMID 36866272, 2023). "In addition to AhR, which was highly active in the MEPs of tumor-bearing mice, we determined RUNX1 levels." (PMID 37919525, 2023). "AHR mRNA levels are elevated in many types of cancer when compared with normal tissues (including ccRCC), and AHR has important roles in regulating cellular proliferation, invasion, migration, and immunity that help drive tumour initiation, promotion, progression, and metastasis." (PMID 36725335, 2023). "Conflicting reports on the functions of AhR in cancer emphasized the necessity of understanding the mechanisms and the biological contexts (tissues and genetic alterations) that drive AhR-dependent tumor suppression." (PMID 37106727, 2023). "The downregulation of AHR in PBMCs of PDAC patients may have implications for the immune response against the tumour." (PMID 37760608, 2023). "Therefore, AhR stimulated the expression of tumor suppressors and promoted the levels of E-cadherin." (PMID 37830596, 2023). "IHC staining of two representative tumor specimens revealed that a high expression level of TMPRSS2 was accompanied by a high expression level of nuclear AhR and IL18, while a low expression level of TMPRSS2 was associated with a low expression level of nuclear AhR and IL18." (PMID 36975376, 2023). "Moreover, the AHR also exerts tumor-suppressive effects and has been shown to inhibit tumor formation and metastasis." (PMID 37696456, 2023). "AhR may be constitutively active in tumors and promote their development because it is overexpressed in various tumor types." (PMID 38068712, 2023). "Furthermore, additional AhR-regulated mechanisms clearly contribute to cancer progression through enhancing cell survival/suppression of apoptosis, altered tumor microenvironment, reduction of contact inhibition and increased angiogenesis." (PMID 37696458, 2023). "However, the role of AHR in the processes of tumor initiation and development remains to be elucidated." (PMID 35687267, 2023). "The researchers utilized a microbial transplantation technique and found that the presence of indole-producing bacterial microbes in the gastrointestinal environment facilitated tumor growth, enhanced the AhR transcriptional response, and encouraged PDAC immunosuppression of TME formation." (PMID 37943609, 2023). "Moreover, oxidative stress and aryl hydrocarbon receptor (AHR) have been demonstrated to upregulate CD39, which governs the function of tumor-associated macrophages." (PMID 37287049, 2023). "Similar to that in the AhR deficiency CRC xenograft mouse model, the inhibitory effect of A. muciniphila on tumorigenesis was not impaired in AhR-deficient ApcMin/+ mouse model, as shown by reduced tumor number in large intestine and small intestine." (PMID 37781044, 2023). "In total, 8 out of 12 tumours in the Low AHR group were well differentiated (G1 or G2)." (PMID 37760608, 2023). "Importantly, the number of CD4+ and CD8+ cells was significantly higher in the tumor-draining lymph nodes in AhR-silenced-MOC1-implanted mice." (PMID 37830596, 2023). "In addition to its many other functions, the ligand-activated transcription factor aryl hydrocarbon receptor (AHR) is an important regulator of tumor progression." (PMID 37696456, 2023). "Thus, in this genetic mouse model for colon tumorigenesis, AhR-mediated suppression of the Wnt signaling pathways are major tumor suppressor-like responses." (PMID 38651159, 2023). "In addition, kynurenine acts via AHR to degrade the adhesion molecule E-cadherin, resulting in enhanced tumor invasion, which is reduced by 1-MT, probably consistent with a role for IDO1 or IDO2." (PMID 37296860, 2023).